EGR1 (early growth response 1)
Description:
Transcriptional regulator. Recognizes and binds to the DNA sequence 5'-GCG(T/G)GGGCG-3'(EGR-site) in the promoter region of target genes (By similarity). Binds double-stranded target DNA, irrespective of the cytosine methylation status. Regulates the transcription of numerous target genes, and thereby plays an important role in regulating the response to growth factors, DNA damage, and ischemia. Plays a role in the regulation of cell survival, proliferation and cell death. Required for normal progress through mitosis and normal proliferation of hepatocytes after partial hepatectomy. Mediates responses to ischemia and hypoxia; regulates the expression of proteins such as IL1B and CXCL2 that are involved in inflammatory processes and development of tissue damage after ischemia. Regulates biosynthesis of luteinizing hormone (LHB) in the pituitary (By similarity). Regulates the amplitude of the expression rhythms of clock genes: BMAL1, PER2 and NR1D1 in the liver via the activation of PER1 (clock repressor) transcription. Regulates the rhythmic expression of core-clock gene BMAL1 in the suprachiasmatic nucleus (SCN) (By similarity).
Synonyms: NGFI-A; ZNF225; 225; TIS8; AT225; G0S30; ZIF268; KROX-24; ZIF-268
Tractability: PROTAC: UniProt records ubiquitination sites on it. Other modalities: a drug acting on it is in phase 2 or 3 trials.
Target class: Transcription factor
Gene: Protein-coding gene on chromosome 5 (138,465,479 to 138,469,303, forward strand). Ensembl gene ENSG00000120738.
Subcellular location: Nucleus; Cytoplasm
Subcellular location (Human Protein Atlas): Nucleoplasm
Pathways (Reactome):
Signal Transduction: NGF-stimulated transcription; Regulation of PTEN gene transcription
Immune System: Interferon alpha/beta signaling
Gene Ontology:
Molecular function: DNA binding; DNA-binding transcription activator activity, RNA polymerase II-specific; DNA-binding transcription factor activity; double-stranded methylated DNA binding; hemi-methylated DNA-binding; histone acetyltransferase binding; promoter-specific chromatin binding; protein binding; RNA polymerase II cis-regulatory region sequence-specific DNA binding; RNA polymerase II transcription regulatory region sequence-specific DNA binding; sequence-specific DNA binding; sequence-specific double-stranded DNA binding; transcription cis-regulatory region binding; zinc ion binding; DNA-binding transcription factor activity, RNA polymerase II-specific; enzyme binding
Biological process: cellular response to interleukin-8; interleukin-1-mediated signaling pathway; positive regulation of DNA-templated transcription; positive regulation of gene expression; positive regulation of miRNA transcription; positive regulation of post-translational protein modification; positive regulation of transcription by RNA polymerase II; regulation of protein sumoylation; cellular response to heparin; cellular response to mycophenolic acid; circadian regulation of gene expression; circadian temperature homeostasis; estrous cycle; glomerular mesangial cell proliferation; locomotor rhythm; long-term memory; positive regulation of chemokine production; positive regulation of gene expression via chromosomal CpG island demethylation; positive regulation of glomerular metanephric mesangial cell proliferation; positive regulation of hormone biosynthetic process; positive regulation of interleukin-1 beta production; regulation of neuron apoptotic process; regulation of progesterone biosynthetic process; regulation of transcription by RNA polymerase II; response to hypoxia; and 5 more
Cellular component: chromatin; cytoplasm; nucleoplasm; nucleus
Genetic constraint (gnomAD): Loss-of-function variants: 8 observed, 31.24 expected, observed/expected ratio (o/e) 0.26, 90% interval 0.15 to 0.46. The upper end of that interval is the gene's LOEUF score, 0.46, which puts it in group 2 of 6, group 1 being the genes least tolerant of losing a copy. Missense variants: 568 observed, 762.26 expected, observed/expected ratio (o/e) 0.75, 90% interval 0.69 to 0.8. Synonymous variants: 334 observed, 327.02 expected, observed/expected ratio (o/e) 1.02, 90% interval 0.93 to 1.12.
Homologues: Orthologues: chimpanzee EGR1 (99% identical), macaque EGR1 (99% identical), pig EGR1 (95% identical), dog EGR1 (94% identical), rabbit EGR1 (93% identical), rat Egr1 (92% identical), guinea pig EGR1 (92% identical), mouse Egr1 (91% identical), tropical clawed frog egr1 (69% identical), Caenorhabditis elegans egrh-3 (15% identical). Paralogues in human: EGR2 (35% identical), EGR3 (34% identical), EGR4 (23% identical), WT1 (19% identical).
Diseases named in the same sentence as EGR1 in open-access papers:
EGR1 is named in the same sentence as 385 diseases in open-access papers, as found by Europe PMC text mining. Sharing a sentence is not in itself a finding about the gene and the disease. The quoted sentences say what the papers report.
breast carcinoma (152 papers, 2005 to 2026). "Intriguingly, we identified EGR1 to be significantly downregulated, which is implicated in breast cancer resistance and an important epigenetic regulator in the methylation context, but whose function in HER2-positive breast cancer has yet to be understood." (PMID 40946111, 2025). "Survival analysis revealed upregulated EGR1 was remarkably associated with favorable relapse-free survival (RFS) among breast cancer patients." (PMID 38654350, 2024). "EGR1 has been implicated in the inhibition of cell cycle progression in breast cancer through transcriptional repression of cyclin D1, D2, and D333,34." (PMID 33436746, 2021). "Recent studies have demonstrated the in breast cancer EGR1 defects are associated with poor prognosis, which is independent of subtype." (PMID 32714860, 2020). "Activation of SRF causes breast cancer cells to switch the active state of a bi-stable feedback loop, by transcriptionally repressing ERα and activating the transcription factor EGR1, which in turn leads to the secondary activation of GDNF." (PMID 29614078, 2018). "A decrease of the expression or the deletion of the EGR1 gene in human is linked to the occurrence of non-small cell lung carcinoma and breast carcinoma, while its activation has growth-inhibiting and suppressing roles in tumorigenesis." (PMID 28531178, 2017). "When the expression of Egr-1 and c-FLIP was studied in colon and breast cancer cell lines, we found that high Egr-1 expression often associates with high c-FLIP expression, especially c-FLIPS." (PMID 20087343, 2010). "Because it upregulates several tumor suppressor genes, EGR1 is also considered to be a tumor suppressor, and lower EGR1 expression has been associated with poorer outcomes in many cancer types, including non-small-cell lung cancer, osteosarcoma, glioma and breast cancer." (PMID 33346749, 2020). "Thus, we integrated data from metabolomic and transcriptomic analyses of ER+ MCF7-derived breast cancer cells that are antiestrogen sensitive (LCC1) or resistant (LCC9) that resulted in a gene-metabolite network associated with EGR1 (early growth response 1)." (PMID 29228577, 2017). "Based on the Human Protein Atlas (HPA) database, we found that MIDN, NR4A1, PSMC1, and EGR1 were all positively expressed in liver cancer, pancreatic cancer, urothelial cancer, breast cancer, and melanoma." (PMID 40002690, 2025). "On the other hand, in glioma and breast cancer cells, ATF5 promotes EGR1 expression via its association with p300 and binding to ATF5 response elements, which contribute to the proliferation and survival of cancer cells." (PMID 40124511, 2025). "Recent studies reveal ERK1/2 promotes breast cancer progression by phosphorylating EGR1 (Ser383/Thr387), enhancing its nuclear translocation and transcriptional activity." (PMID 40519297, 2025). "In an in vivo study, wild-type MSCs and EGR1-deficient MSCs were separately prepared from wild-type (Egr1+/+) and Egr1-null (Egr1−/−) mice, and then co-injected subcutaneously with 4T1 mouse breast cancer cells." (PMID 40676710, 2025). "In certain cancers, including breast cancer and hepatocellular carcinoma, EGR1 has been found to inhibit cancer cell growth and migration." (PMID 39866235, 2025). "Our qPCR data demonstrate that knockdown of EGR1 significantly reduces METTL3 expression while upregulating LINC01133 levels in ER+ breast cancer cells." (PMID 40641925, 2025). "NRF2 overactivation by early growth response 1 (EGR1) leads to increased HMOX1 transcription in breast cancer, providing a survival advantage to the cancer cells and promoting resistance to therapy." (PMID 41333220, 2025).
breast carcinoma (continued). "For instance, EGR1 has been documented to suppress migration and proliferation in breast cancer and hepatocellular carcinoma cells." (PMID 39866235, 2025). "A previous breast cancer study showed that EGR1 plays a role in cancer suppression and endocrine therapy by regulating PTEN, which also inhibits endometrial proliferation." (PMID 39044249, 2024). "TBX2 started mechanisms of normal growth control by recruiting a series of inhibitory compounds to combine with reactive promoter of EGR1, which led to uncontrolled proliferation of breast cancer cells." (PMID 38413457, 2024). "EGR1 usually acts as a transcription factor and has a tumor suppressor function in various tumors, including breast cancer." (PMID 39044249, 2024). "The positive relationship between the apoptotic markers (cleaved caspase 3 and EGR1) and the efficacy of Taxol chemotherapy in breast cancer patients, highlights the role of Asp132-cleavage of AURKA." (PMID 38994036, 2024). "Recent studies have shown that the overexpression of Egr-1 in breast cancer can suppress cell migration and invasion." (PMID 37046823, 2023). "Previous studies have shown that EGR1, as a transcriptional factor, can promote the activation of p21cip1/waf1 in glioma, breast cancer, melanoma and gastric cancer." (PMID 37012388, 2023). "miRNA-2110, an onco-suppressor with the ability to suppress breast cancer and neuroblastoma, was down-regulated after Egr-1 knockdown for 48 and 72 h." (PMID 36207572, 2022). "Increased expression of Egr1 is associated with the apoptosis of squamous cell carcinoma cells and breast cancer cells, while knocking down Egr1 mitigates apoptosis." (PMID 36292956, 2022). "Meanwhile, early growth response 1 (EGR1) is a stress response transcription factor whose expression is lost in breast cancer." (PMID 35159030, 2022). "Expression of this miRNA has been found to be increased by ionizing radiation and its over-expression has been correlated with expression levels of EGR1 in a certain breast cancer cell line." (PMID 36582800, 2022). "Here in our study, we detected generally repressed expression of FGF2 and its related genes enriched in the breast cancer pathway, including EGR1, in peripheral blood lymphocytes of certain MDD individuals." (PMID 34667146, 2021). "EGR1 was significantly decreased in breast cancer tissues compared to normal breast tissues, and EGR1 gene expression was negative correlation with breast cancer stages." (PMID 33472669, 2021). "For the rs2236007 site, the risk allele G downregulates the PAX9 gene via recruiting the suppressive transcription factor EGR1 and results in malignancy and poor prognosis for breast cancer patients." (PMID 34889888, 2021). "The transcriptional control of Nm23-H1 by CTCF and EGR1 provides a mechanism for their ability to inhibit the metastatic process of breast cancer cells." (PMID 33436746, 2021). "Through inhibition of MAPK phosphorylation, the nuclear concentration of EGR1 can be reduced while the proliferation of breast cancer cells can be significantly suppressed." (PMID 33842351, 2021). "In prostate, kidney, and stomach cancers, EGR1 stimulates the growth of tumor cells, but is a tumor suppressor in esophageal cancer, breast cancer, and rhabdomyosarcoma." (PMID 33990633, 2021). "NME1 can be transcriptionally regulated by a multitude of transcription factors, in particular by CTCF and EGR1, which potentially drive Nm23-H1 expression in breast cancer cells to promote a less metastatic phenotype." (PMID 33436746, 2021). "Studies showed that the reduction of EGR1 protein level can cooperate with anti‐oestrogen to inhibit the proliferation of breast cancer cells; and EGR1 is expected to be an important target to prevent or reverse endocrine resistance." (PMID 34651424, 2021).
breast carcinoma (continued). "This study indicates that loss of Nm23-H1 in aggressive breast cancer is apparently caused by downregulation of CTCF and EGR1, which potentially drive Nm23-H1 expression to promote a less invasive phenotype." (PMID 33436746, 2021). "In brief, the results indicate that the rs2236007 downregulates the gene expression of PAX9 by affecting the binding of suppressive transcription factor EGR1 and contributes to the malignancy of breast cancer with a poor prognosis for breast cancer patients." (PMID 34889888, 2021). "In conclusion, the present study demonstrates that chrysoeriol reduces TNFα-induced upregulation of CYP19 aromatase expression via inhibition of ERK MAPK-mediated EGR-1 expression in MCF-7 breast cancer cells." (PMID 33053908, 2020). "In this study, we investigated the role of the transcription factor early growth response gene 1 (EGR-1) in the induction of CYP19 expression in response to TNFα stimulation in ER-positive MCF-7 breast cancer cells." (PMID 33053908, 2020). "The role of transcription factor early growth response gene 1 (EGR-1) in CYP19 expression was assessed using the short-hairpin RNA (shRNA)-mediated knockdown of EGR-1 expression in estrogen receptor-positive MCF-7 breast cancer cells." (PMID 33053908, 2020). "In all subtypes of breast cancer, the mRNA levels of EGR1, EGR2, and EGR3 were all lower in malignant breast tissues compared with normal tissues." (PMID 33614706, 2020). "Studies have shown that a high expression level of EGR1 can significantly inhibit the proliferation of breast cancer, non-small cell lung cancer, and oesophageal cancer." (PMID 31000722, 2019). "It implies that increasing the expression level of EGR1 can suppress the development of breast cancer." (PMID 31874629, 2019). "Breast cancer cells that have undergone hypoxic conditions can induce Egr1 and hypoxia-inducible factor-1α." (PMID 31399076, 2019). "MIR2052HG associated with EGR1 and facilitated its binding to the LMTK3 gene promoter to activate LMTK3 expression, which in turn, promoted ERα-positive breast cancer cell growth." (PMID 30944027, 2019). "An earlier study showed that EGR1 directly inhibits MMP2 in breast cancer cells by binding to its promoter." (PMID 30845713, 2019). "The positive correlation between EGR1 and PN-1 protein levels was supported by using Spearman correlation analysis in 1104 breast cancer tissues (StarBase database)." (PMID 31501409, 2019). "DIM-C-Pyr-4 also induced Egr-1 in breast cancer cells, and RNA interference assays showed that these responses were dependent on COUP-TFI and the Sp proteins (Sp1 and Sp3)." (PMID 30866413, 2019). "Egr-1 facilitates the transcription of miR-20b, thereby inducing the growth and progression of breast cancer." (PMID 30400241, 2018). "Previous studies have shown that EGR1 interacts with TBX2 in breast cancer and represses the function of EGR1 as tumor suppressor." (PMID 29719592, 2018). "We further show that these MOFs are also effective at delivering DNAzyme (an ssDNA of 33 nucleotides) to MCF-7 human breast cancer cells, and inhibit the expression of the EGR-1 gene." (PMID 29615605, 2018). "For example, it has been demonstrated that Egr-1 controls the transcription of miR-20b in breast cancer." (PMID 30400241, 2018). "Our data demonstrated that SFN increases the expression of EGR1 in melanoma cells, which is in agreement with recent breast cancer data." (PMID 28864908, 2018). "EGR1 is a mammalian nuclear transcription factor with an indispensable role in breast cancer proliferation, migration, chemoinvasion, and angiogenesis." (PMID 29212169, 2017). "Collectively, these findings indicate that EGR1 is an important regulator of breast cancer cell metabolism and is a promising target to prevent or reverse endocrine resistance." (PMID 29228577, 2017). "Disruption of the ER signaling pathway can affect EGR1 levels in ER+ breast cancer cells and tumors." (PMID 29228577, 2017).